MDFIC (MyoD family inhibitor domain containing)
Description:
Required to control the activity of various transcription factors through their sequestration in the cytoplasm. Retains nuclear Zic proteins ZIC1, ZIC2 and ZIC3 in the cytoplasm and inhibits their transcriptional activation (By similarity). Modulates the expression from cellular promoters. Binds to the axin complex, resulting in an increase in the level of free beta-catenin. Affects axin regulation of the WNT and JNK signaling pathways. Involved in the development of lymphatic vessel valves (By similarity). Required to promote lymphatic endothelial cell migration, in a process that involves down-regulation of integrin beta 1 activation and control of cell adhesion to the extracellular matrix. Regulates the activity of mechanosensitive Piezo channel. (Microbial infection) Modulates the expression from viral promoters. Down-regulates Tat-dependent transcription of the human immunodeficiency virus type 1 (HIV-1) LTR by interacting with HIV-1 Tat and Rev and impairing their nuclear import, probably by rendering the NLS domains inaccessible to importin-beta (PubMed:12944466, PubMed:16260749, Ref.6). Also stimulates activation of human T-cell leukemia virus type I (HTLV-I) LTR.
Synonyms: hIC; MDFIC1; LMPHM12
Tractability: Small molecule: a structure with a bound ligand is known. Antibody: UniProt places it where antibodies can reach, with medium confidence; its Gene Ontology location is reachable by antibodies, with medium confidence. PROTAC: ubiquitination databases record sites on it.
Gene: Protein-coding gene on chromosome 7 (114,921,746 to 115,019,917, forward strand). Ensembl gene ENSG00000135272.
Subcellular location: Nucleus, nucleolus (Isoform 1); Cytoplasm (Isoform 2); Secreted
Subcellular location (Human Protein Atlas): Golgi apparatus; Nucleoplasm
Gene Ontology:
Molecular function: cyclin binding; DNA-binding transcription factor binding; protein binding; Tat protein binding
Biological process: positive regulation of DNA-templated transcription; positive regulation of viral transcription; regulation of JNK cascade; regulation of Wnt signaling pathway; negative regulation of DNA-templated transcription; negative regulation of protein import into nucleus; regulation of gene expression
Cellular component: cytoplasm; nucleoplasm; extracellular region; nucleolus; nucleus
Genetic constraint (gnomAD): Loss-of-function variants: 15 observed, 15.35 expected, observed/expected ratio (o/e) 0.98, 90% interval 0.65 to 1.5. The upper end of that interval is the gene's LOEUF score, 1.5, which puts it in group 6 of 6, group 1 being the genes least tolerant of losing a copy. Missense variants: 273 observed, 242.92 expected, observed/expected ratio (o/e) 1.12, 90% interval 1.02 to 1.24. Synonymous variants: 91 observed, 92.23 expected, observed/expected ratio (o/e) 0.99, 90% interval 0.83 to 1.17.
Homologues: Orthologues: chimpanzee MDFIC (99% identical), macaque MDFIC (97% identical), rabbit MDFIC (91% identical), pig MDFIC (89% identical), mouse Mdfic (82% identical), guinea pig MDFIC (80% identical), rat Mdfic (80% identical), dog MDFIC (55% identical), zebrafish mdfic (55% identical), tropical clawed frog mdfic (48% identical). Paralogues in human: MDFI (40% identical), MDFIC2 (19% identical).
Diseases named in the same sentence as MDFIC in open-access papers:
MDFIC is named in the same sentence as 29 diseases in open-access papers, as found by Europe PMC text mining. Sharing a sentence is not in itself a finding about the gene and the disease. The quoted sentences say what the papers report.
lung disease (2 papers, 2024 to 2025). "Applying Standigm ASKTM to idiopathic pulmonary fibrosis (IPF), a complex lung disease, we focused on genes (AMFR, MDFIC and NR5A2) identified through KG evidence." (PMID 38349059, 2024).
neuroblastoma (2 papers, 2015 to 2019). Neuroblastoma (NB) is the most common solid, extracranial childhood tumor. "Kaplan-Meier plots showed a significant association between increased expression of CFHR3, MDFIC, CSMD3, FOXP2, or RALYL (genes with gains in coding regions) and poor OS in patients with neuroblastoma." (PMID 26159519, 2015). "SK-N-MC neuroblastoma cells derive from the supraorbital area and express FOXP2 and MDFIC constitutively." (PMID 31046704, 2019).
channelopathy (1 paper, 2025). Channelopathies are a group of diseases caused by the dysfunction of ion channel subunits or their interacting proteins. "Lastly, the inactivation can be modulated by extrinsic cues, such as MDFIC, and the channelopathy mutants of PIEZO channels often cause a slower inactivation rate." (PMID 40668110, 2025). "Indeed, electrophysiological studies showed that co-expression of these channelopathy mutants with MDFIC resulted in significantly reduced mechanosensitivity and inactivation rate." (PMID 40668110, 2025). "Here, we report several near-atomic resolution cryo-EM structures of fast-inactivating wild-type human PIEZO1 (hPIEZO1) and its slow-inactivating channelopathy mutants with or without its auxiliary subunit MDFIC." (PMID 40668110, 2025).
chordoma (1 paper, 2021). Chordomas are rare malignant tumors arising from embryonic remnants of the notochord in axial skeleton. "The purpose of this study was to investigate the modulatory function of lncRNA MDFIC-7 in chordoma and to elucidate its underlying mechanisms." (PMID 34621682, 2021). "In the present study, we sought to clarify the regulatory role of the lncRNA MDFIC-7/miR-525-5p/ARF6 axis in chordoma progression and examine the potential underlying mechanisms." (PMID 34621682, 2021). "We demonstrate that the lncRNA MDFIC-7/miR-525-5p/ARF6 axis contributes to the tumorigenesis of human chordoma and facilitates the Warburg effect and cancer progression." (PMID 34621682, 2021). "In our study, we found that lncRNA MDFIC-7 was mainly located in the cytoplasm of chordoma cells, and we identified miR-525-5p as a target of lncRNA MDFIC-7 by bioinformatics analyses and dual luciferase reporter assay." (PMID 34621682, 2021). "Consistent with the ECAR results, lncRNA MDFIC-7 knockdown enhanced OCR in chordoma cells, and the promotion of OCR was reversed by ARF6 overexpression." (PMID 34621682, 2021). "Our findings showed that the significant up-regulation of lncRNA MDFIC-7 in chordoma patient tumor tissues compared with adjacent normal tissues was accompanied by a concomitant decrease in miR-525-5p." (PMID 34621682, 2021). "In this study, we demonstrated that lncRNA MDFIC-7 knockdown suppressed cell proliferation, tumorigenicity and the Warburg effect (aerobic glycolysis) of chordoma cells both in vitro and in vivo through inhibiting the expression of ARF6." (PMID 34621682, 2021). "To investigate the role of lncRNA MDFIC-7 in regulating the tumor progression of chordoma, we first inhibited lncRNA MDFIC-7 expression in U-CH1 and U-CH2 cells using lentivirus expressing shRNA-MDFIC7." (PMID 34621682, 2021). "We first clarified the function of lncRNA MDFIC-7 in chordoma cells." (PMID 34621682, 2021). "The results showed that lncRNA MDFIC-7 is mainly distributed in the cytoplasm of chordoma cells." (PMID 34621682, 2021). "It was suggested that lncRNA MDFIC-7 could act as a competing endogenous RNA (ceRNA) in human chordoma." (PMID 34621682, 2021). "Our results demonstrated that lncRNA MDFIC-7 knockdown significantly inhibited chordoma cell proliferation in vitro, suggesting that the lncRNA MDFIC-7 exerts tumor promoting activity in chordoma and indicating that lncRNA MDFIC-7 may be a potential prognostic indicator for chordoma." (PMID 34621682, 2021). "In summary, our study provides the first identification of the lncRNA MDFIC-7/miR-525-5p/ARF6 regulatory network in cell proliferation and glucose metabolism in chordoma." (PMID 34621682, 2021). "A significant correlation between lncRNA MDFIC-7 and ARF6 expression in chordoma was found." (PMID 34621682, 2021). "However, the roles of lncRNA MDFIC-7 and miRNA-525-5p in chordoma progression have not been reported." (PMID 34621682, 2021).
colorectal cancer (1 paper, 2020). A primary or metastatic malignant neoplasm that affects the colon or rectum. "In this study, we provide the first evidence that MDFI and MDFIC are involved in colorectal cancer." (PMID 32457453, 2020). "Hence, we examined the role of MDFI and MDFIC in colorectal cancer cells." (PMID 32457453, 2020). "Finally, we wondered if MDFI and MDFIC may not only be involved in colorectal cancer, but also in neoplasms of other tissues." (PMID 32457453, 2020). "To assess if MDFI or MDFIC can affect cancer cells, we overexpressed these proteins in human HCT116 colorectal cancer cells and then examined their growth." (PMID 32457453, 2020). "Further, MDFI and MDFIC interacted with Jumonji C domain-containing (JMJD) 1 A, a histone demethylase and epigenetic regulator involved in colorectal cancer." (PMID 32457453, 2020). "Indeed, HIC1 phenocopied MDFIC in suppressing HCT116 cell growth and clonogenic activity, suggesting that a MDFIC→HIC1 axis can restrain colorectal cancer development." (PMID 32457453, 2020). "Similar to colorectal cancer, MDFI was up- and MDFIC downregulated in breast, ovarian and prostate cancer, but both were overexpressed in brain, gastric and pancreatic tumors that implies MDFIC to also promote tumorigenesis in certain tissues." (PMID 32457453, 2020).
colorectal tumors (1 paper, 2020). "This is based on the following evidence: First, we showed that MDFI is overexpressed, while MDFIC is downregulated in colorectal tumors, and high MDFI but low MDFIC levels are associated with more aggressive disease." (PMID 32457453, 2020). "Lastly, it is noteworthy that JMJD1A has been implicated in breast, gastric, ovarian and prostate cancer, suggesting that the interaction of JMJD1A with MDFI/MDFIC is relevant beyond colorectal tumors." (PMID 32457453, 2020). "Together, these data suggest that MDFI up- and MDFIC downregulation are connected to colorectal tumor formation and possibly also the aggressiveness of the disease." (PMID 32457453, 2020). "We discovered that MDFI is up- and MDFIC downregulated in colorectal tumors." (PMID 32457453, 2020). "In addition, we discovered changes in the expression pattern of MDFI and MDFIC in colorectal tumors." (PMID 32457453, 2020). "Using published microarray data, we observed that, identical to colorectal tumors, MDFI and MDFIC exhibited up- and downregulation, respectively, in prostate, breast and ovarian cancer." (PMID 32457453, 2020).
gastric cancer (1 paper, 2020). A primary or metastatic malignant neoplasm involving the stomach. "Furthermore, we observed again that HIC1 and MDFIC mRNA levels were strongly correlated in breast, ovarian and gastric cancer and accordingly, like MDFIC, HIC1 was downregulated in breast and ovarian tumors and upregulated in gastric tumors." (PMID 32457453, 2020).
gastric tumors (1 paper, 2020). "However, both MDFI and MDFIC were upregulated in brain, pancreatic and gastric tumors." (PMID 32457453, 2020).
leukaemia (1 paper, 2021). "Importantly, in our GWAS, which was also adjusted for white blood cell counts, we found association signals near genes involved in leukaemia and lymphoma development (CRK, BAK1, CDK6, MDFIC, BIK) as well as a significant enrichment of pathways related to immune cell proliferation." (PMID 33385171, 2021).
pulmonary fibrosis (1 paper, 2024). Chronic progressive interstitial lung disorder characterized by the replacement of the lung tissue by connective tissue, leading to progressive dyspnea, respiratory failure, or right heart failure. "We selected four genes (NR5A2, AMFR, MDFIC and AXIN) that were upregulated more than 2-fold in the pulmonary fibrosis mouse model compared with the levels in the control group." (PMID 38349059, 2024).
rectal mucinous adenocarcinomas (1 paper, 2020). "The Cancer Genome Atlas (TCGA) data set21 revealed that MDFI mRNA was significantly upregulated in cecum, colon, colon mucinous, rectal and rectal mucinous adenocarcinomas compared to normal colon and rectum, while MDFIC was on average downregulated." (PMID 32457453, 2020).
cancer (3 papers, 2015 to 2021). A tumor composed of atypical neoplastic, often pleomorphic cells that invade other tissues. "Our fourth, puzzling discovery is the fact that MDFIC expression in cancer can be either up- or downregulated depending on the organ." (PMID 32457453, 2020). "Altogether, our data suggest a tumor modulating function for MDFI and MDFIC in colorectal and other cancers that may involve their interaction with JMJD1A and a MDFIC→HIC1 axis." (PMID 32457453, 2020).
tumor (3 papers, 2017 to 2021). "Perplexingly, despite their high homology, they appear to act in opposite ways, namely MDFI as a tumor promoter and MDFIC as a repressor." (PMID 32457453, 2020). "This implicates that MDFI may generally perform tumor promoting activities, whereas MDFIC might tissue-specifically inhibit or stimulate tumorigenesis." (PMID 32457453, 2020). "As such, the results of the shown RNA interference experiments do not allow us to strengthen or refute the hypothesis that MDFI exerts tumor-promoting and MDFIC tumor-suppressing activities." (PMID 32457453, 2020). "Presently, it is essentially unknown whether MDFI and MDFIC play any role in tumor formation." (PMID 32457453, 2020). "To further investigate the effects of the lncRNA MDFIC-7/miR-525-5p/ARF6 axis on tumorigenicity in vivo, we generated a xenograft tumor mouse model using U-CH1 cells infected with lentivirus to downregulate lncRNA MDFIC-7." (PMID 34621682, 2021). "Similar MDFI up- and MDFIC downregulation was observed in other microarray data sets, and MDFI appears to be also more expressed in metastatic compared to primary tumor sites." (PMID 32457453, 2020). "The results showed that lncRNA MDFIC-7 was significantly upregulated in tumor tissues compared to adjacent non-tumor tissues." (PMID 34621682, 2021).
MDFIC also shares sentences with these, for which no sentence is quoted: cardiovascular diseases (2 papers); asthma (1); atherosclerosis (1); Cognitive impairment (1); colon cancer (1); idiopathic pulmonary fibrosis (1); infection (1); intellectual disabilities (1); lung carcinoma (1); lymphedema (1); lymphoma (1); neurodegenerative disease (1); ovarian carcinoma (1); ovarian tumors (1); prostate carcinoma (1); viral infection (1).